CEP55 (centrosomal protein 55)
Diseases named in the same sentence as CEP55 in open-access papers (continued):
Sharing a sentence is not in itself a finding about the gene and the disease.
lung cancer (23 papers, 2009 to 2025). A malignant neoplasm involving the lung. "High expression of CEP55 has also been associated with poor prognosis of non‐small cell lung cancer, gallbladder cancer, and endometrial cancer." (PMID 38661103, 2024). "CEP55 is widely expressed in cancers, notably lung cancer, and has been identified as a gene strongly linked to prognosis." (PMID 39023191, 2024). "CEP55 was reported to be overexpressed in lung cancer tissues and associated with cell migration and invasion, as well as participate in the VEGF-A/PI3K/AKT pathway." (PMID 26615423, 2016). "Notably, CEP55 is associated with poor prognosis in lung cancer." (PMID 39023191, 2024). "In clinical studies, CEP55 overexpression has been reported in multiple cancer types, including lung cancer." (PMID 39023191, 2024). "Accumulating evidence indicates that CEP55 expression was elevated in some other tumors, such as liver cancer, cervical cancer, and lung cancer." (PMID 37274251, 2023). "Xie et al32 found that CEP55 expression was up-regulated in lung cancer by PCR and immunohistochemistry." (PMID 36404510, 2022). "High expression of the centrosomal protein CEP55 has been correlated with clinicopathological parameters across multiple human cancers, such as thyroid cancer, liver cancer, lung cancer and epithelial ovarian carcinoma." (PMID 33952272, 2021). "Previously, CEP55 has proven to be a useful biomarker for a variety of cancers, including lung cancer." (PMID 32437446, 2020). "For instance, upregulated expression of CEP55 was reported to modulate the invasion and migration of lung cancer, nasopharyngeal carcinomas, and oral cavity squamous cell carcinoma." (PMID 30096813, 2018). "Since CEP55 stimulates cell migration and invasion in oral and lung cancers, we assayed in vitro migration and invasion in the MDA‐MB‐231 derivatives and observed a significant reduction compared to control cells (P < 0.001)." (PMID 30108112, 2018). "Overexpression of CEP55 has been reported in colon cancer, head and neck cancer, lung cancer, oral cavity squamous cell carcinoma and HCC." (PMID 30089483, 2018). "CEP55 was a key factor of abscission, which was found to be upregulated and correlated with the tumor stage and prognosis in multiple types of human cancers, including lung cancer and colon and liver cancer." (PMID 34055036, 2021). "Moreover, overexpression of CEP55 was shown to regulate EMT through the VEGF-A/PI3K/AKT pathway in lung cancer." (PMID 26615423, 2016). "Transwell migration and invasion assays revealed that CEP55 knockdown significantly inhibited the migration and invasion of Colon Tumor 26 (CT26) and Lewis lung cancer cell line (3LL) cells (p < 0.05)." (PMID 40236779, 2025). "qRT-PCR confirmed that the expression level of CDKN3, MKI67, CEP55, SPAG5, AURKA, TOP2A were highly expressed in lung cancer tissues." (PMID 35178291, 2022). "The experimental results show that CEP55, NMU, CAV1, TBX3, FBLN1and SYNM have significantly different expression in lung cancer." (PMID 36404510, 2022). "However, the targeting relationships of KIG15 with has-mir-3677, and CEP55 with has-mir-34b were also predicted in the functional analysis of miRNA in patients with gastric antral vascular ectasia and expression meta-analysis of lung cancer miRNA targets, respectively." (PMID 32582275, 2020). "In particular, several studies have shown that CEP55 plays an important role in regulating EMT in oral cavity squamous cell carcinoma, lung cancer, and ovarian cancer." (PMID 30096813, 2018). "Third, our research primarily focused on validating CEP55 function in lung cancer, lacking extensive verification across other cancer types." (PMID 40236779, 2025). "In summary, through WGCNA and differential gene expression analysis, our study generated the significant genes, ASPM, CDCA8, CENP5, CEP55, and PLK1 that may be biomarkers and has potential for treatment in HIV‐infected lung cancer." (PMID 35608130, 2023).
lung cancer (continued). "Among them, five genes (ASPM, CDCA8, CENPF, CEP55, and PLK1) were present in both three hub gene lists (intersection gene, DEGs, and WCGNA module) suggesting that these five genes may become key genes involved in HIV‐infected lung cancer." (PMID 35608130, 2023). "Previous studies have confirmed that CEP55 expression could distinguish cancers from control tissues in 21 cancer types, including hepatocellular, breast, liver, colorectal, lung cancer, etc., but CEP55 expression is not well documented in glioma, especially GBM." (PMID 40504854, 2025).
hepatocellular carcinoma (21 papers, 2009 to 2025). A malignant tumor that arises from hepatocytes. "For example, increased expression of CEP55 promotes anchorage-free proliferation of hepatocellular carcinoma by stimulating PI3K/AKT activity." (PMID 40723362, 2025). "We constructed and validated a CEP55-related risk model for hepatocellular carcinoma (HCC) and explored the correlations between CEP55 expression and HCC molecular subtypes." (PMID 37484531, 2023). "CEP55 can also activate the PI3K/AKT pathway as an oncogenic mechanism in hepatocellular carcinoma, and through the same mechanism, CEP55 was found to activate the proliferation of human glioma U251 cells, osteosarcoma, and esophageal squamous cell carcinoma." (PMID 37175004, 2023). "We demonstrated that distinct hepatocellular carcinoma molecular subtypes can be identified based on CEP55 expression." (PMID 37484531, 2023). "SPAG5 promoted the progression of hepatocellular carcinoma through CEP55-mediated activation of the PI3K/AKT pathway." (PMID 35138218, 2022). "SPAG5, which interacts with centrosomal protein CEP55 resulting in the phosphorylation of AKT at Ser473, promotes hepatocellular carcinoma growth via CEP55-mediated Phosphatidyl inositol -3- hydroxykinase (PI3K)/(protein kinase B) AKT pathway." (PMID 34796102, 2021). "Mounting evidence shows that CEP55 is highly expressed in multiple cancers, such as colon cancer, hepatocellular carcinoma and bladder cancer." (PMID 32587798, 2020). "Overexpression of gene CEP55 has been observed in variety of solid tumors, including colon cancer, bladder cancer, hepatocellular carcinoma, gastric cancer, esophagus adenocarcinoma and ovarian carcinoma." (PMID 30987631, 2019). "Consistent with their roles in malignancy, CEP55 is upregulated in hepatocellular carcinoma and its overexpression induces anchorage-independent growth, enhanced cell growth at low serum levels and induction of tumourigenesis in nude mice." (PMID 19287496, 2009). "Next, a literature search was conducted to focus on proteins specifically associated with liver disease in general, which selected 20 proteins, seven of which (i.e., CEP55, CLIC1, EPS15L1, G6PD, KIF11, SLC1A5, and TK1) were found to be specifically associated with hepatocellular carcinoma." (PMID 37627157, 2023). "Indeed, downregulation of miR-363-3p allows SPAG5 to exert its oncogenic activity initiating PI3K/AKT pathway via CEP55 interaction in hepatocellular carcinoma." (PMID 33230261, 2021). "The PI3K/AKT pathway is upregulated when CEP55 is overexpressed, which encourages the invasion and motility of cells in hepatocellular carcinoma (HCC) and lung adenocarcinoma (LAC)." (PMID 39911278, 2025). "Several scientists pointed out that CDC20, CEP55, TRIP13, MYBL2 were overexpressed in hepatocellular carcinoma, compared with adjacent normal tissues." (PMID 38297250, 2024). "It has been reported that the interaction between CEP55 and SPAG5 triggered the phosphorylation of AKT at Ser473 and activated the PI3K/AKT pathway to exhibit pro-hepatocellular carcinoma activities." (PMID 37274251, 2023). "High levels of CEP55 form a complex with PI3K to activate PI3K/AKT activity, thereby enhancing the non-anchored growth of hepatocellular carcinoma (HCC)." (PMID 37887301, 2023). "In addition, the CEP55 expression was significantly related to the infiltration level of B cells, CD4+ T cells, CD8+ T cells, macrophages, neutrophils, and dendritic cells in hepatocellular carcinoma (HCC)." (PMID 32337246, 2020).
liver cancer (16 papers, 2020 to 2025). An epithelial or non-epithelial malignant neoplasm that arises from the liver. "CEP55 expression had been recognized to be an independent risk factor in predicting liver cancer patient survival upon univariate and multivariate analyses." (PMID 32337246, 2020). "Meanwhile, CEP55 was identified as the risk factor to independently predict overall survival (OS) for patients with liver cancer upon multivariate analysis." (PMID 32337246, 2020). "For the first time, we used the TIMER database to uncover the association between CEP55 expression and TIICs in liver cancer." (PMID 32337246, 2020). "This study was performed to investigate the association of CEP55 expression with liver cancer and explore potential underlying mechanisms." (PMID 32337246, 2020). "The present study improves our understanding of the association between CEP55 and liver cancer, but some limitations still exist." (PMID 32337246, 2020). "We found that CEP55 expression is negatively correlated with its DNA methylation level, suggesting that DNA hypomethylation is one of the underlying causes for the overexpression of CEP55 in liver cancer." (PMID 32337246, 2020). "We demonstrate that overexpression of α‐catenin contributes to liver cancer cell migration through physical binding and protein stabilization of CEP55." (PMID 37381005, 2023). "Next, we wanted to clarify the mechanistic connection between α‐catenin and CEP55 in liver cancer cells." (PMID 37381005, 2023). "Together, we here identified several new α‐catenin interacting partners such as PDLIM7 and CEP55, which exclusively interact with α‐catenin in the cytoplasm of liver cancer cells." (PMID 37381005, 2023). "Using mass spectrometry, we identified several new α‐catenin interaction partners in the cytosol of liver cancer cells, including the cytokinesis regulator centrosomal protein 55 (CEP55)." (PMID 37381005, 2023). "Analyzing cancers by tissue revealed that the CEP55 protein was overexpressed in several human cancers, where patients with thyroid, testis, and liver cancers came at the top of this list." (PMID 37175004, 2023). "CEP55 was also negatively correlated with the clinical outcome in multiple human tumors, including liver cancer, non-small cell lung cancer, esophageal squamous cell carcinoma, and ovarian epithelial carcinoma." (PMID 37175004, 2023). "The overexpression of SPAG5 promoted tumor growth and metastasis, as SPAG5 interacts with CEP55 to trigger the phosphorylation of AKT at Ser473, causing liver cancer." (PMID 34055888, 2021). "In order to explore the potential mechanism of overexpression in liver cancer, we first used DNA methylation and gene expression data of liver cancer patients in the TCGA database to analyze the correlation between DNA methylation and gene expression of CEP55." (PMID 32337246, 2020). "In this study, we included both HCC and CCA patients from The Cancer Genome Atlas (TCGA) to investigate the prognostic significance of CEP55 expression and DNA methylation of CEP55 in liver cancer." (PMID 32337246, 2020). "Data obtained from The Cancer Genome Atlas (TCGA) was used to investigate CEP55 expression, its prognostic value, the potential mechanisms of its upregulation, CEP55-related pathways, and its biological functions in liver cancer." (PMID 32337246, 2020). "Then, joint prognostic survival analysis was performed and we found that the combination of CEP55 methylation and its expression had a significant correlation with the prognosis of liver cancer patients." (PMID 32337246, 2020). "The correlation between CEP55 and tumor-infiltrating immune cells (TIICs) in liver cancer was determined by using Tumor Immune Estimation Resource (TIMER)." (PMID 32337246, 2020). "High CEP55 expression was also closely related to poor prognosis in patients with liver cancer, as it promoted the migration and invasion of liver cancer cells by regulating JAK2-STAT3-MMP signaling." (PMID 32149111, 2020).
liver cancer (continued). "CEP55 plays an important role in cytoplasmic division, tumor stage, aggressiveness, metastasis and poor prognosis in many tumor types such as breast, lung, colon and liver cancers." (PMID 37138854, 2023). "Therefore, we combined the methylation and the expression of CEP55 and classified liver cancer patients into the CEP55 hypermethylation and low expression group and the CEP55 hypomethylation and high expression group based on the median values." (PMID 32337246, 2020). "CEP55 may serve as a candidate treatment target for it is a determinant of prognosis and immune infiltration in liver cancer patients." (PMID 32337246, 2020). "In addition, we investigated the correlation between CEP55 and tumor-infiltrating immune cells (TIICs) in liver cancer using Tumor Immune Estimation Resource (TIMER)." (PMID 32337246, 2020). "Furthermore, the expression of CEP55 in 58 paired liver cancer samples and adjacent normal samples was analyzed, and our findings suggested a marked overexpression of CEP55 for liver tumor (p = 2.649e − 17)." (PMID 32337246, 2020). "CEP55 overexpression showed correlation with the dismal prognosis in liver cancer patients." (PMID 32337246, 2020). "In addition, high CEP55 expression in liver cancer was positively related to advanced stage, high histological grade, and high T classification." (PMID 32337246, 2020). "In addition, we performed survival analysis to investigate the prognostic value of the CEP55 methylation level in liver cancer patients." (PMID 32337246, 2020). "Although we have made a validation of survival analysis and protein expression of CEP55 based on the data from the ICGC, GEO, and HPA databases, further experiments are needed to explore the molecular mechanisms associated with CEP55 in liver cancer progression and prognosis." (PMID 32337246, 2020). "DNA hypomethylation might contribute to the overexpression of CEP55 in liver cancer." (PMID 32337246, 2020). "CEP55 might serve as a candidate treatment target for liver cancer." (PMID 32337246, 2020). "Subgroup analysis results suggested that high CEP55 expression predominantly affected the prognosis of patients with clinical stage I/II, T1/T2, N0, and M0 disease, thus implying the special prognostic value of CEP55 and its potential contribution to the accurate treatment of liver cancer." (PMID 32337246, 2020). "We found that CEP55 may be helpful in guiding treatment selection for liver cancer patients." (PMID 32337246, 2020). "DNA hypomethylation of CEP55 may contribute to its overexpression in liver cancer." (PMID 32337246, 2020). "CEP55 expression in liver tumor samples and adjacent normal samples was also compared using data directly obtained from TCGA, and the result demonstrated that CEP55 expression was markedly increased within liver cancer samples compared to normal liver samples (p = 1.397e − 29)." (PMID 32337246, 2020). "Therefore, we suppose that the CEP55 methylation level does not directly affect the prognosis of liver cancer patients, but by regulating the expression of CEP55 and then affecting the prognosis of liver cancer patients." (PMID 32337246, 2020). "However, the results showed that the CEP55 methylation level did not affect the prognosis of liver cancer patients." (PMID 32337246, 2020). "In summary, CEP55 is overexpressed in liver tumor tissues compared to normal liver tissues and CEP55 overexpression is related to dismal prognosis and increased immune infiltration levels of B cells, CD4+ T cells, CD8+ T cells, macrophages, neutrophils, and dendritic cells in liver cancer." (PMID 32337246, 2020).
ovarian carcinoma (14 papers, 2015 to 2025). A malignant neoplasm originating from the surface ovarian epithelium. "In most publications a high CEP55 level has been shown to be associated with unfavorable prognosis of breast and ovarian cancer patients." (PMID 39195269, 2024). "The loss of CEP55 function mediated by RNAi in ovarian cancer cell models indicated that suppression of CEP55 repressed cellular invasion, demonstrating the involvement of CEP55 in enhancing the migratory and invasive activity in ovarian cancer cells." (PMID 26615423, 2016). "Moreover, we investigated the association between the expression of CEP55 protein and clinical manifestations and survival outcomes of a cohort of 213 patients with ovarian cancer." (PMID 26615423, 2016). "The clinical significance of CEP55 as a potential biomarker is verified with the overexpression of CEP55, which has been observed in several cancer types, including breast, colorectal, liver, lung, and ovarian cancers." (PMID 40723362, 2025). "In order to analyse a potential CEP55 localization to cellular endosomes, EGFP‐CEP55 was expressed in ovarian cancer OVCAR‐8 cells, and CEP55 localization was assessed by fluorescence microscopy." (PMID 39976236, 2025). "The thymus- and testis-specific scaffold protein Centrosomal Protein 55 (CEP55) is overexpressed in many types of cancer, including ovarian cancer, where it is associated with unfavorable prognosis." (PMID 39195269, 2024). "Taken together, these results indicate that the heterogeneity of chromosomal aberrations within the ovarian cancer cell lines was reduced after knock-down of CEP55." (PMID 39195269, 2024). "Through cbioportal analysis of how the genes were correlated with prognosis, we observed improved overall survival rate of ovarian cancer patients with CEP55 variation, with a statistically significant difference (p = 0.012)." (PMID 34734085, 2021). "Taken together, these findings provide with essential, reliable evidence for the clinical significance of CEP55 as an independent prognostic marker to identify ovarian cancer patients with poor prognosis." (PMID 26615423, 2016). "CEP55 siRNA1 and CEP55 siRNA3 duplexes obviously reduced CEP55 protein in both ovarian cancer cell lines, and these more efficient siRNAs were therefore chosen for subsequent studies." (PMID 26615423, 2016). "To further investigate the role of CEP55 in the invasion of ovarian cancer, we transfected SKOV3 and TOV-21G cells with 200 pmol siRNA for 24 h, which offered the best silencing efficiency in our preliminary experiments." (PMID 26615423, 2016). "CEP55 expression in ovarian cancer patients was associated with survival time, with the patients expressing low CEP55 in their ovarian cancer lesions surviving much longer than those with high CEP55 expression (P < 0.001)." (PMID 26615423, 2016). "Here, we suppressed CEP55 expression by siRNA and demonstrated, for the first time, that downregulation of CEP55 remarkably repressed ovarian cancer cellular invasion and reversed EMT." (PMID 26615423, 2016). "In our cohort, we examined the expression of CEP55 mRNA and protein in ovarian cancer cell lines and ovarian cancer samples." (PMID 26615423, 2016). "Statistical analyses were employed to detect the correlation between CEP55 expression and the clinicopathological characteristics of ovarian cancer patients." (PMID 26615423, 2016). "CEP55 was significantly upregulated in ovarian cancer cell lines and lesions compared with normal cells and adjacent noncancerous ovarian tissues." (PMID 26615423, 2016). "Western blotting results indicated that CEP55 protein expression was low in normal ovarian tissue, benign ovarian cancer tissue, and borderline ovarian cancer tissue, while it was high in ovarian carcinoma tissues from patients at different clinical stages." (PMID 26615423, 2016). "Survival analysis found that CEP55 and CCNE1 may be associated with the prognosis of ovarian cancer." (PMID 34734085, 2021).